ENSG00000270299 (novel protein)
Gene: Protein-coding gene on chromosome 20 (646,626 to 675,800, reverse strand). Ensembl gene ENSG00000270299.
Genetic constraint (gnomAD): Loss-of-function variants: 4 observed, 3.93 expected, observed/expected ratio (o/e) 1.02, 90% interval 0.48 to 1.84. That is too few expected variants to judge how well the gene tolerates losing a copy. Missense variants: 97 observed, 60.14 expected, observed/expected ratio (o/e) 1.61, 90% interval 1.37 to 1.88. Synonymous variants: 47 observed, 25.86 expected, observed/expected ratio (o/e) 1.82, 90% interval 1.4 to 1.97.